ADAMTS3 (ADAM metallopeptidase with thrombospondin type 1 motif 3)
Description:
Cleaves the propeptides of type II collagen prior to fibril assembly. Does not act on types I and III collagens.
Synonyms: KIAA0366; ADAMTS-4; HKLLS3
Tractability: Antibody: UniProt places it where antibodies can reach, with high confidence; its Gene Ontology location is reachable by antibodies, with high confidence; UniProt predicts a signal peptide or a membrane-spanning region. PROTAC: its protein half-life has been measured.
Gene: Protein-coding gene on chromosome 4 (72,280,969 to 72,569,221, reverse strand). Ensembl gene ENSG00000156140.
Subcellular location: Secreted; Secreted, extracellular space, extracellular matrix
Subcellular location (Human Protein Atlas): Intermediate filaments; Predicted to be secreted
Pathways (Reactome):
Disease: Defective B3GALTL causes PpS
Extracellular matrix organization: Collagen biosynthesis and modifying enzymes
Metabolism of proteins: O-glycosylation of TSR domain-containing proteins
Gene Ontology:
Molecular function: endopeptidase activity; protein binding; metalloendopeptidase activity; zinc ion binding; metallopeptidase activity
Biological process: collagen biosynthetic process; positive regulation of vascular endothelial growth factor signaling pathway; protein processing; vascular endothelial growth factor production; collagen catabolic process; collagen fibril organization; extracellular matrix organization; proteolysis; supramolecular fiber organization
Cellular component: extracellular exosome; extracellular region; extracellular matrix
Genetic constraint (gnomAD): Loss-of-function variants: 64 observed, 117.6 expected, observed/expected ratio (o/e) 0.54, 90% interval 0.44 to 0.67. The upper end of that interval is the gene's LOEUF score, 0.67, which puts it in group 2 of 6, group 1 being the genes least tolerant of losing a copy. Missense variants: 1,388 observed, 1,488.4 expected, observed/expected ratio (o/e) 0.93, 90% interval 0.89 to 0.98. Synonymous variants: 462 observed, 508.26 expected, observed/expected ratio (o/e) 0.91, 90% interval 0.84 to 0.98.
Homologues: Orthologues: chimpanzee ADAMTS3 (99% identical), macaque ADAMTS3 (97% identical), pig ADAMTS3 (92% identical), rabbit ADAMTS3 (92% identical), dog ADAMTS3 (91% identical), mouse Adamts3 (88% identical), rat Adamts3 (88% identical), tropical clawed frog adamts3 (76% identical), zebrafish adamts3 (70% identical). Paralogues in human: ADAMTS2 (55% identical), ADAMTS14 (55% identical), ADAMTS9 (29% identical), ADAMTS7 (28% identical), ADAMTS18 (28% identical), ADAMTS16 (28% identical), ADAMTS6 (27% identical), ADAMTS12 (27% identical), ADAMTS20 (26% identical), ADAMTS10 (26% identical), ADAMTS17 (24% identical), ADAMTS15 (24% identical), and 13 more.
Diseases named in the same sentence as ADAMTS3 in open-access papers:
ADAMTS3 is named in the same sentence as 35 diseases in open-access papers, as found by Europe PMC text mining. Sharing a sentence is not in itself a finding about the gene and the disease. The quoted sentences say what the papers report.
Hennekam syndrome (6 papers, 2020 to 2024). Hennekam syndrome is characterized by the association of lymphoedema, intestinal lymphangiectasia, intellectual deficit and facial dysmorphism. "In humans, variants in ADAMTS3 cause the more benign Hennekam lymphangiectasia–lymphedema syndrome 3, characterized by polyhydramnios and congenital lymphedema of lower extremities." (PMID 39409761, 2024). "Some of the nsSNPs that we have described have been shown to be pathogenic in patients with Hennekam syndrome due to mutations in the ADAMTS3 gene." (PMID 37322437, 2023). "Hennekam Lymphangiectasia–Lymphedema Syndrome 3 (HKLLS3) is a rare genetical disorder caused by mutations in a few genes including ADAMTS3." (PMID 37322437, 2023). "As ADAMTS3 variants are associated with abnormally expanded lymphatic vessels in Hennekam syndrome, ADAMTS3 might control tissue shape and integrity by regulating BM composition." (PMID 35584218, 2022). "Our results provide data on the ADAMTS3 gene's pathogenic nsSNPs, protein 3D structure, potential PTMs sites, and gene–gene interaction, which could aid future research into the gene's function in Hennekam syndrome and other related disorders." (PMID 37322437, 2023). "These SNPs have the potential to contribute to the pathophysiology of ADAMTS3-related disorders, such as Hennekam syndrome." (PMID 37322437, 2023). "Although these 19 ADAMTS3 nsSNPs have not yet been identified in individuals with Hennekam syndrome, they would be considered pathogenic nsSNPs if they were found in the future." (PMID 37322437, 2023). "Finally, patients with Hennekam syndrome, resulting from mutations in CCBE1, FAT4 or ADAMTS3, exhibit diffuse lymphatic dysplasia which also affects lymph flow in the gut." (PMID 33147779, 2020). "These five nsSNPs (G298R, C567Y, A370T, C567R, and G374S) could be used as a marker for other patients with mutations in the ADAMT3 gene, even if they have not yet been associated with Hennekam syndrome caused by ADAMTS3." (PMID 37322437, 2023). "This is the first-ever study of ADAMTS3 gene polymorphism, and the predicted nsSNPs in ADAMST3, some of which have not been reported yet in patients, will serve for diagnostic purposes and further therapeutic implications in Hennekam syndrome, contributing to better diagnosis and treatment." (PMID 37322437, 2023). "In contrast, phenotypes in Ehlers–Danlos syndrome and Hennekam syndrome patients completely differed and involved different organs, although ADAMTS2 and ADAMTS3 possess the same procollagen N-propeptidase domains." (PMID 32183147, 2020).
lymphedema (4 papers, 2016 to 2025). Excess fluid collection in tissues, causing swelling. "A single amino acid substitution in ADAMTS3, identified from a lymphedema patient, was associated with abnormal CCBE1 localization." (PMID 28687807, 2017). "Previous studies indicate that ADAMTS3 loss of function results in lymphoedema." (PMID 31095560, 2019). "Interestingly, in both the ADAMTS3 knock out mouse and cases of human Hennekam lymphangiectasia-lymphedema, craniofacial abnormalities are reported in conjunction with aberrant lymphatic development." (PMID 31095560, 2019). "As in Adamts3−/− embryos, lymphedema is massive and similarly characterized by the absence of lymphatics normally forming around E13–E13.5." (PMID 26446156, 2016). "Since the ADAMTS3 R565Q allele was heterozygous in the patient and since it did not completely abolish the interaction of ADAMTS3 with CCBE1, it may not alone explain the lymphedema phenotype, suggesting that it acts as a modifier of the lymphedema phenotype in this family." (PMID 28687807, 2017).
osteosarcoma (4 papers, 2020 to 2026). A usually aggressive malignant bone-forming mesenchymal neoplasm, predominantly affecting adolescents and young adults. "ADAMTS3 is involved in the alteration of osteosarcoma matrices, and the single nucleotide polymorphism (SNP) of the ADAMTS3 gene is an independent prognostic biomarker for cutaneous melanoma." (PMID 32884571, 2020). "They provided the first findings for the SP1-related transcriptional regulation of ADAMTS3 and collagen genes in osteosarcoma cell lines." (PMID 35847857, 2022). "SP1-related transcriptional regulation of ADAMTS3 gene expression in osteosarcoma cell models." (PMID 32102222, 2020).
breast carcinoma (3 papers, 2021 to 2024). "It has also been observed that the increased expression of ADAMTS3 gene takes a major part in the development of myocardial infarction, osteoarthritis, and breast cancer." (PMID 33851708, 2021). "For instance, ADAMTS3 is necessary for lymphangiogenesis through proteolytic processing of VEGF‐C, and suppresses early breast cancer invasion through degradation of fibronectin." (PMID 37929635, 2024). "Together with ADAMTS3, ADAMTS10 expression appeared reduced in breast cancer tissues." (PMID 35886011, 2022).
glioma (2 papers, 2023 to 2024). A benign or malignant brain and spinal cord tumor that arises from glial cells (astrocytes, oligodendrocytes, ependymal cells). "Further, we examined the correlation between ADAMTS3 expression and glioma patient prognosis using Gravendeel datasets." (PMID 36514188, 2023). "We also confirmed that the mRNA level of multiple glioma‐related stemness markers decreases when ADAMTS3 expression is suppressed." (PMID 36514188, 2023). "Accordingly, the ADAMTS3 level was more highly expressed in Grade IV (GBM) samples than in low‐grade glioma samples." (PMID 36514188, 2023). "In conclusion, we found that increased ADAMTS3 expression in glioma stem cells is related to GBM aggressiveness and tumor development." (PMID 36514188, 2023). "Moreover, High ADAMTS3 expression (p = 0.03) and age (p = 0.001) were found to be factors influencing glioma patients' survival in multivariate analysis." (PMID 36514188, 2023). "In addition to the Gravendeel dataset, the inverse correlation between ADAMTS3 expression and overall survival was also present in The Cancer Genome Atlas (TCGA) and Chinese Glioma Genome Atlas (CGGA) datasets." (PMID 36514188, 2023). "As such, these data demonstrate that ADAMTS3 is correlated with poor prognosis in glioma patients." (PMID 36514188, 2023). "ADAMTS3 level was remarkably higher in GSCs than in NHA, glioma cell lines, and their matched differentiated tumor cells." (PMID 36514188, 2023). "ADAMTS3 was highly upregulated in GSCs compared to NHA and glioma cell lines, according to qRT‐PCR analysis." (PMID 36514188, 2023). "ADAMTS3 mRNA expression levels in normal human astrocyte (NHA), glioma, and GSCs cell lines were compared." (PMID 36514188, 2023).
breast tumors (1 paper, 2015). "We identified three new focal rearrangements in grade III/LVI-positive breast tumors: 4q13 and 11q11 amplifications (harboring the ADAMTS3 and the HSD17B12 genes, respectively) and a homozygous deletion at 12p12.3 (containing, among others, the RERGL gene)." (PMID 25391423, 2015).
cerebrovascular diseases (1 paper, 2024). "There were 6 genes related to cardiovascular and cerebrovascular diseases, which were Fgd3, Myoz3, AC095693.1, Adamts3, PDGFA and PDGFRα." (PMID 38195688, 2024).
dental caries (1 paper, 2012). The decay of a tooth, in which it becomes softened, discolored, and/or porous. "The role of ADAMTS3 in cariogenesis is unknown; however, given its role in tooth development in mouse, it is plausible that this gene affects susceptibility to dental caries." (PMID 23259602, 2012).
endothelial dysfunction (1 paper, 2019). In vascular diseases, endothelial dysfunction is a systemic pathological state of the endothelium (the inner lining of blood vessels) and can be broadly defined as an imbalance between vasodilating and vasoconstricting substances produced by (or acting on) the endothelium. "Besides, Angiopoietin-2 several other endothelial dysfunction markers, like PAI-1, ADAMTS3, d-dimer, sPECAM-1, TF and TM were found to correlate with viral load, but only in CCHF patients." (PMID 31357521, 2019).
glioblastoma (1 paper, 2023). The most malignant astrocytic tumor (WHO grade IV). "We proposed that ADAMTS3 is a potential target for glioblastoma therapy." (PMID 36514188, 2023).
Intellectual disability (1 paper, 2020). "We highlight ADAMTS3, ANKRD17 and RNU4ATAC9P as candidate genes for intellectual disability, growth retardation and congenital heart defect." (PMID 32299451, 2020).
invasive carcinoma (1 paper, 2024). A carcinoma that is not confined to the epithelium, and has spread to the surrounding stroma. "As in this context ADAMTS3 directly cleaves FN, the loss of ADAMTS3 expression results in FN accumulation, which promotes cancer cell migration via the interaction with α5 integrin, resulting in the transition to invasive carcinoma." (PMID 38948119, 2024).
leukemia (1 paper, 2017). A malignant (clonal) hematologic disorder, involving hematopoietic stem cells and characterized by the presence of primitive or atypical myeloid or lymphoid cells in the bone marrow and the blood. "Using RNA sequencing, we found that genes associated with AML subtypes, such as RYR3, RHAG, PCDH9, ANK1, ADAMTS3, and DLC1, were significantly up-regulated in the leukemia cells of two responders, but not in the 3 non-responders." (PMID 28900115, 2017).
lung carcinoma (1 paper, 2025). "The lactate-related risk score, constructed using ADAMTS3, FADS2, and RTBDN, was further explored to assess their expression and prognostic value for radiotherapy patients with lung cancer across multiple databases." (PMID 40861806, 2025). "The increased methylation of ADAMTS3, FADS2 and RTBDN was found in lung cancer tissues, potentially contributing to their downregulation." (PMID 40861806, 2025).
mastitis (1 paper, 2019). Inflammation of breast tissue during lactation or postpartum due to an obstructed duct or infection. "The NPFFR2 gene (neuropeptide FF receptor 2) along with GC and ADAMTS3 (ADAM metallopeptidase with thrombospondin type 1 motif 3) genes were reported previously to be located within a QTL region affecting clinical mastitis in Norwegian Red dairy cattle." (PMID 31311492, 2019).
rheumatoid arthritis (1 paper, 2021). A chronic, systemic autoimmune disorder characterized by inflammation in the synovial membranes and articular surfaces. "CCBE1 ADAMTS3, VEGFC, FLTR4, and GJC2 are thought to be related with either Hennekam disorder or its related symptoms in many diseases, including rheumatoid arthritis." (PMID 34234628, 2021).
schizophrenia (1 paper, 2020). A major psychotic disorder characterized by abnormalities in the perception or expression of reality. "Patients 2's duplication encompasses 11 OMIM genes, of which RPS17, HOMER2, and ADAMTS3 have already been described as schizophrenia-associated genes in the literature." (PMID 33510659, 2020).
Sepsis (1 paper, 2021). Sepsis is defined as life-threatening organ dysfunction caused by a dysregulated host response to infection. "ADAMTS3 was found to be the most active gene in the PPI network in the first periods of patients transferring from sepsis to sepsis induced ARDS." (PMID 33818300, 2021). "The PPI indicated one key gene, ADAMTS3, played a crucial role with the most interactions during the first period of patients transferring from sepsis to sepsis-induced ARDS." (PMID 33818300, 2021).
tendinopathy (1 paper, 2023). "In regard to the expression of metalloprotease-encoding genes, increased expression of MMP2, MMP14, MMP16, ADAMTS2, ADAMTS3 as well as downregulation of MMP10 has also been found in tendinopathy." (PMID 38001919, 2023).
tumor (8 papers, 2015 to 2026). "The ADAMTS3 gene belongs to the ADAMTS metalloproteinase family that has been implicated in tumor progression." (PMID 25391423, 2015). "When compared to shNT‐control infected GSC11 spheres, mice infected with ADAMTS3 knockdown had significantly reduced tumor formation and had significantly longer median survival rates." (PMID 36514188, 2023). "Previous studies demonstrated that ADAMTS3 is expressed in mast cells, and mast cells have both tumor-promoting and tumor-inhibiting effects, thus leading to different prognoses in different tumors." (PMID 36033493, 2022). "Furthermore, we have shown that ADAMTS3 knockdown cells lost their tumor formation ability in the orthotopic GBM mouse models." (PMID 36514188, 2023). "Also, we examined the effect of ADAMTS3 knockdown on self‐renewal and tumor formation ability in vitro and in vivo of GSCs isolated from primary GBM tissues." (PMID 36514188, 2023). "Hence, these findings indicate that ADAMTS3 expression is critical in maintaining tumorigenesis by ensuring self‐renewal and tumor initiation ability of GSCs." (PMID 36514188, 2023). "Given the role of aberrant DNA methylation in cancer-related dysregulation, the UALCAN database was utilized to investigate the relationship between the expression patterns of ADAMTS3, FADS2, and RTBDN and methylation levels in both normal and tumor tissues." (PMID 40861806, 2025). "ADAMTS3 and FADS2 exhibited downregulation in tumor tissues compared to normal lung tissues, whereas RTBDN displayed an opposite trend." (PMID 40861806, 2025). "Knockdown of ADAMTS3 suppresses GSC's proliferation, self‐renewal activity, and tumor formation in vivo." (PMID 36514188, 2023). "Interestingly, knockdown of ADAMTS3 disrupted GSC's proliferation, self‐renewal activity, and tumor formation in vivo." (PMID 36514188, 2023). "Given the importance of metalloproteinases in the formation and progression of GBM,20, 21, 22 we examined the ADAMTS3 gene, which is increased in GSC and may have a role in tumor growth." (PMID 36514188, 2023).
cancer (5 papers, 2016 to 2025). A tumor composed of atypical neoplastic, often pleomorphic cells that invade other tissues. "Collectively, the increased expression of ADAMTS3 in the GBM could be linked to the vascular structure, ECM organization, and cancer‐related signaling." (PMID 36514188, 2023). "It would be most interesting also to evaluate whether ADAMTS3 is also involved in lymphatics homeostasis during the adulthood and in the abnormal lymphangiogenesis observed in several pathological conditions, including cancer and metastasis dissemination." (PMID 26446156, 2016).
infection (2 papers, 2018 to 2023). The state of being infected such as from the introduction of a foreign agent such as serum, vaccine, antigenic substance or organism. "We identified 11 genes that were significantly altered after infection with both viruses, and among these genes, 6 were up-regulated after infection (Chl1, Nlrp12, Plk1, Cyfip2, Adamts3, and Pdzk1)." (PMID 30713529, 2018).
neurodevelopmental disorder (1 paper, 2020). A behavioral and cognitive disorder with onset during the developmental period that involves impaired or aberrant development of intellectual, motor, or social functions. "Inhibition of ADAMTS-3 may therefore reduce the amount of inactive Reelin and help to improve the symptoms seen in neurodevelopmental disorders." (PMID 32982694, 2020).
respiratory disease (1 paper, 2019). "This discovery changes how we view respiratory disease predisposition in the dog, offers potential genetic screens and highlights a new biological function for ADAMTS3." (PMID 31095560, 2019). "In contrast, the ADAMTS3 genotype does not segregate with weight, a suspected respiratory disease risk factor." (PMID 31095560, 2019).
ADAMTS3 also shares sentences with these, for which no sentence is quoted: genetic diseases (2 papers); congenital stationary night blindness (1); cutaneous melanoma (1); influenza (1); mesothelioma (1); myocardial infarction (1); Obesity (1); osteoarthritis (1); primary lymphedema (1); renal cell carcinoma (1); Thrombocytopenia (1).